IL18 (interleukin 18)
Diseases named in the same sentence as IL18 in open-access papers (continued):
Sharing a sentence is not in itself a finding about the gene and the disease.
Sepsis (continued). "ROC analysis demonstrated strong predictive performance for sepsis/septic shock using RIPK1 (AUC = 0.81), IL-18 (AUC = 0.71), and A20 (AUC = 0.71); conversely, caspase-8 was inversely associated with sepsis (AUC = 0.32)." (PMID 40722817, 2025). "Toll-like receptors (TLRs) are commonly activated receptors in sepsis, leading to the activation of NF-κB and the subsequent release of inflammatory factors, such as TNF-α, IL-1β, IL-6, and IL-18." (PMID 41311552, 2025). "We observed prominent necroptosis activation in sepsis—evidenced by elevated RIPK-1, IL-1β, and IL-18 levels and suppressed caspase-8 levels." (PMID 40722817, 2025). "Median values of IL-6, IL-18, and GDF15 were significantly higher in the sepsis and septic shock groups, compared to the non-sepsis group." (PMID 40681771, 2025). "Many proinflammatory cytokines, such as IL-1, IL-6, IL-8, IL-12, IL-18, TNF-a, and IFN-r, are highly expressed, leading to cytokine storms after sepsis develops." (PMID 40136690, 2025). "One study found that exosomes derived from sepsis patients’ blood can upregulate miR-885-5p in AC16 cells, downregulate homeobox containing 1 (HMBOX1) and increase IL-1β and IL-18, further promoting pyroptosis of AC16 cells." (PMID 40041174, 2025). "TNF, IL-18, IL-10, IL-1Ra and s-CHI3L1 were significantly higher in the septic shock group, compared with the sepsis and non-sepsis groups." (PMID 40681771, 2025). "The MAIT cell‐activating cytokines IL‐12, IL‐15 and IL‐18, as well as TNF, IFNγ and IL‐17A, cytokines known to be produced by MAIT cells, were elevated in the plasma of sepsis patients as well as non‐sepsis patients, compared with non‐infected controls." (PMID 40041474, 2025). "Therefore, IL-18 could be a potential biomarker for predicting sepsis-associated AKI but not for other related causes." (PMID 40429966, 2025). "Our data support a model whereby a few elements of cytokine information—TNF plus IL-18, IFN-γ or IL-1β—suffice to explain a large fraction of the molecular and cellular effects of sepsis across tissues." (PMID 38191855, 2024). "As sepsis progresses, the levels of NLRP3 and IL‐18 also increase, further aggravating renal tubular damage and leading to progressive decline in renal function." (PMID 39692606, 2024). "The results showed that sepsis significantly promoted NLRP3, Pro Caspase-1, ASC and IL-18 mRNA levels, increased NLRP3, Pro Caspase-1, Cleaved Caspase-1 and ASC protein expression, whereas pretreatment with 6 and 30 mg/kg taraxerone attenuated these effects." (PMID 39543653, 2024). "A recent study demonstrated that sepsis-exos increased the level of miR-885-5p, decreased HMBOX1, elevated IL-1β and IL-18, and promoted pyroptosis in AC16 cells." (PMID 39770410, 2024). "The effects of TNF plus IL-18, IFN-γ or IL-1β encompassed a high proportion of sepsis biomarker genes, 45.7% (118/258), 43.8% (113/258) or 32.6% (84/258), respectively, compared to the other 12 cytokine pairs tested (8.1% ± 7.3% s.d.)." (PMID 38191855, 2024). "Furthermore, the baseline excessive pro-inflammatory cytokines, such as TNF-α, IL-6, IL-1α, IL-1β, and IL-18, released after hepatic cell damage in NASH or further stage, might predispose NAFLD patients to cytokine storm in the setting of sepsis, resulting in worse outcomes." (PMID 39407795, 2024). "In distinguishing between sepsis and AOSD, the sensitivity and specificity of IL-18 were 88% and 78% for a cutoff value of 148.9 pg/mL in one study and 91.7% and 99.1% for a cutoff value of 366.1 pg/mL in another study." (PMID 39767141, 2024). "We focused on six cytokines that play a major role in sepsis: IFN-γ, IL-1β, IL-6, IL-10, IL-18 and TNF6." (PMID 38191855, 2024). "In the context of sepsis, NLRP3 functions by recruiting and activating caspase-1, leading to release of IL-1β and IL-18, initiating a cascade of inflammatory reactions that ultimately leads to substantial inflammation-induced damage and multi-organ failure." (PMID 39364223, 2024).
Sepsis (continued). "Inflammatory cytokines such as IL-1, IL-6, IL-18 and TNF-α are critically involved in the pathogenesis of sepsis." (PMID 37494665, 2023). "Consensus cluster analysis we successfully classified sepsis patients into two distinct groups based on the expression of 8 hub genes (IGFBP7, GMFG, IL10, IL18, ETS2, HGF, CD55, and MMP9)." (PMID 38259686, 2023). "To address if sepsis alters the bystander/innate function of naïve CD8 T cells, we stimulated splenocytes derived from Sham- or CLP-treated mice with IL-12/IL-18 ± IL-2 or PMA/ionomycin for 5 hours." (PMID 37824591, 2023). "proved that the activity of bone marrow-derived macrophages in sepsis mice was inhibited after treatment with HMGB1, leading to the increased release of IL-1β and IL-18 through caspase-11-dependent pyroptosis." (PMID 35572571, 2022). "In addition, measurement of PTX3 in combination with cytokine levels (IL-6 and IL-18), and other routine clinical parameters rapidly available in ED (e.g., age, urea), can provide a promising approach for 90-days mortality prediction for sepsis patients, better than the use of a single biomarker." (PMID 36189302, 2022). "There has never been a multicenter study in eastern Indonesia on KIM-1, IL-18, and IGFBP-7 in urine as biomarkers to predict the occurrence of AKI in children treated with sepsis in the pediatric intensive care unit (PICU) in Makassar, South Sulawesi." (PMID 36545669, 2022). "In the setting of medical and non-sepsis patients, urinary NGAL had better predictive performance than urinary IL-18, urinary L-FABP, and urinary TIMP-2 × IGFBP-7: 0.3." (PMID 36371256, 2022). "Relative to sepsis controls, patients with HBD + DIC were characterized by increased expression of ferritin, IL-18, sCD163, sCD25, IL-6, and CXCL10, consistent with a biomarker signature of macrophage activation." (PMID 35190900, 2022). "This review focuses on a number of kidney injury biomarkers, such as CysC, NAGAL, KIM-1, L-FABP, IL-18, suPAR, and [TIMP-2] • [IGFBP7], which have been widely studied in common clinical settings, such as sepsis, cardiac surgery, and contrast-induced AKI." (PMID 35930243, 2022). "Western blotting revealed that sepsis promoted the expression of NLRP3, IL-18, and GSDMD-N in color tissues, whereas FMT and SCFAs treatment prevented the CLP-induced expression of these proteins." (PMID 36713461, 2022). "This study aimed to observe the role of urinary kidney injury molecule (KIM-1), interleukin (IL-18), and insulin-like growth factor-binding protein 7 (IGFBP-7) levels in predicting acute kidney injury (AKI) in children with sepsis." (PMID 36545669, 2022). "The expression of NLRP3, Caspase-1, GSDMD, IL-1β, and IL-18 was decreased, suggesting that ALDH2 also inhibited pyroptosis in sepsis-induced lung injury." (PMID 35188436, 2022). "The purpose of this study is to determine the role of urinary KIM-1, IL-18, and IGFBP-7 levels in predicting the occurrence of AKI in children with sepsis." (PMID 36545669, 2022). "A previous study showed that IL-18 mediates ischemic acute tubular necrosis in AKI, whereas our study shows that IL-18BP has much stronger correlation with AKI than IL-18 in sepsis." (PMID 35203474, 2022). "MFA, especially at the highest dose, reduced cytokine levels (IL-1β, IL-18, and TNF-α) in the early stages of sepsis, favoring a balance of the immune system and of equilibrium of inflammatory components, crucial for the development of a favorable outcome." (PMID 36333747, 2022). "In the in vitro and in vivo model of sepsis, the up and down molecules of the IL-17 signaling pathway (HMGB1, RAGE, IL-17A, NK-κB) and inflammatory factors (IL-1β, IL-18) were upregulated." (PMID 36406124, 2022). "Sepsis-exos increased the level of miR-885-5p, decreased HMBOX1, elevated IL-1β and IL-18, and promoted pyroptosis in AC16 cells." (PMID 35345489, 2022).
Sepsis (continued). "LPS-stimulated Lcn2-/- mice also exhibit elevated hallmarks of sepsis, including the expression of proinflammatory cytokines such as TNF-α and IL-18, immune cell apoptosis, and systemic organ dysfunction." (PMID 36054235, 2022). "Importantly, circulating IL-18 and mitochondrial DNA, a DAMP associated with NLRP3 inflammasome activation, were significantly elevated in plasma from human patients critically ill with diseases such as sepsis and sepsis-induced ARDS, and significantly associated with ICU mortality." (PMID 36232959, 2022). "We found an increase in the expression of IL-6, IL-8, IL-10, IL-18, IL-33, IP-10, MIF, MIP1a, MIP1β, MIP3a, LEPTIN, GCSF, MCSF, and ESelectin in sepsis plasma compared to w/o sepsis and HC." (PMID 35681439, 2022). "In sepsis, the inflammatory cytokines include tumor necrosis factor-α (TNF-α), interleukin-18 (IL-18), and interleukin-1β (IL-1β)." (PMID 36199375, 2022). "In the current study, activation of the NLRP3 inflammasome accompanied by increased secretion of IL-1β, IL-18, and HMGB1 was noted in CD11c+CD11bintMHC-IIhiCD115−Flt3+ splenic DCs after induction of sepsis." (PMID 34741186, 2021). "It is well established that MCP-1 release is controlled by interleukin-18 (IL-18) and extracellular signal-regulated kinase 1/2 (ERK1/2), and the levels of MCP-1 are higher in patients with sepsis, septic shock, and pneumonia." (PMID 34073235, 2021). "We have previously shown that the combination of serum IL-18 and FGF-2 is a useful biomarker to discriminate between sepsis and adult-onset Still’s disease (AOSD)." (PMID 34654467, 2021). "To further explore the proinflammatory effects of MSN in sepsis, we next performed ELISA to measure the effects of MSN silencing on the production of the inflammatory cytokines TNF-α, IL-6, IL-1β, and IL-18 in medium supernatant of HMECs." (PMID 33628853, 2021). "Overall, all patients had elevated TNF-a and IL-6 levels at initial screening, and most had elevated IL-1β and IL-18, while some had elevated IFN-γ; however, a gradual decrease in levels of all of the cytokines studied was observed upon resolution of sepsis." (PMID 34659208, 2021). "In addition, targeting IL‐18/IL‐1/IL‐17A axis may improve outcomes for human neonates with sepsis." (PMID 33378581, 2021). "It has been reported that serum cytokines such as IL-1β, IL-6, IL-8, IL-10, IL-12, IL-17A, IL-18, interferon gamma (IFN-γ), and TNF-α are elevated in sepsis, but some of these cytokines are also elevated in FMF patients." (PMID 34654467, 2021). "Attenuation of sepsis-induced acute kidney injury was due to the prohibited production of inflammatory cytokines and decrease expression of Caspas-1, NLRP-1, IL-1β, and IL-18 in renal tissues." (PMID 34222479, 2021). "In patients on IMV, the best predictive model for extrapulmonary sepsis included SOFA score, IL-18, and IL-1RA (log-rank P = 0.002), whereas for pulmonary sepsis included PaO2/FiO2, ICAM-1 and IL-1RA (log-rank P = 0.0002)." (PMID 34811434, 2021). "IL-1β and IL-18 are crucial activation elements of the NLRP3 inflammasome during pyroptosis, and their production is known to be activated by I/R and sepsis but suppressed by propofol." (PMID 33260147, 2020). "Cats with sepsis showed significantly higher concentrations of IL-13, MCP-1, and IL-18 compared to cats with septic shock and healthy controls." (PMID 32548135, 2020). "Accordingly, in contrast with inflammatory cytokines such as IL-1β, IL-6, TNF-α, and IFN-γ, elevation of IL-18 has levels been reported to be characteristic of AOSD and, thus, potentially useful for differentiating AOSD from sepsis." (PMID 32381117, 2020). "IL-18 and then FGF-2 were extracted as the most important cytokines for distinguishing AOSD from sepsis (mean decrease accuracy 17.2 and 11.4, respectively)." (PMID 32381117, 2020). "In both sepsis groups at 24 h after CLP, plasma levels of AST and IL-18 had increased two-fold compared to the sham group." (PMID 32295272, 2020).
Sepsis (continued). "Both sepsis groups had higher gene expressions of NLRP3, caspase-11, and IL-1β and lower expression of IL-18 compared to the sham group." (PMID 32295272, 2020). "In the present model of sepsis induced AKI (CLP septic model), serum creatinine, urea, total and direct bilirubin, NGAL and IL18 levels were significantly increased during the experimental period." (PMID 30850654, 2019). "IL18 and NGAL also rose similarly as blood biomarkers to a peak at 72 hours after CLP, proving as potentially related biomarkers for sepsis-induced AKI24." (PMID 30850654, 2019). "In myocardium, TNF and IL-6 were significantly elevated in sepsis, TNF in both ventricles and IL-6 mostly in RV, while IL-1β, IL-18 and C5a were significantly higher in RV compared to LV after PAB (all p<0.05)." (PMID 31247004, 2019). "The other markers already well studied in ICU patients or sepsis (e.g., KIM-1, IL-18, IGFBP-7, and TIMP-2) should be verified in the AP patients." (PMID 31366007, 2019). "Very high levels of IL-18 > 5000 pg/ml were only seen in active AOSD except in 2 other patients, one with chronic lymphatic leukemia (6600 pg/ml) and one with sepsis (5476 pg/ml)." (PMID 30886992, 2019). "Myocardial mRNA levels of IL-1β, IL-6, IL-18, IP-10, E-selectin and PAI-1 were significantly elevated in RV and LV during sepsis compared to PAB, while Caspase-1 was decreased in septic compared to PAB animals (all p<0.05)." (PMID 31247004, 2019). "It was suggested that low miR-150 serum levels identify septic disease in these patients and that miR-150 levels correlate with classical prognosis scores such as SOFA or established markers for sepsis and inflammation such as TNF, IL-10 or IL-18." (PMID 23372743, 2013). "Serum levels of IL-18 increase in response to CPB surgery and in other inflammatory conditions such as sepsis and type 1 diabetes." (PMID 19178691, 2009). "IL-8 and IL-18 on day 1 (r = 0.26 and r = 0.24) and IL-1β on day 5 (r = −0.45) showed correlation in the non-MASLD group, but not in the MASLD group, where TGF-β1 negatively correlated with sepsis severity on day 5 (r = −0.22)." (PMID 40076848, 2025). "Cut-off value of Interleukin-18 (IL-18) with corresponding sensitivity and specificity for distinguishing abdominal sepsis from non-abdominal sepsis at the day of sepsis diagnosis (d0)." (PMID 40510342, 2025). "In addition, MAIT cells can respond to cytokines including IL‐12, IL‐18, IFN‐α and IL‐15,10, 15, 16, 17 all of which are elevated in the blood early in sepsis." (PMID 40041474, 2025). "The results demonstrate that IL-18, IL-6, MCP-1, and IL-10 are increased in sepsis, while IL-18 may serve as an additional biomarker for distinguishing abdominal from non-abdominal sepsis." (PMID 40510342, 2025). "As a sepsis biomarker, sCD25 has been shown to display higher serum concentrations compared to controls, alongside sCD163 and IL-18; however, the author did not perform any multiparameter analysis." (PMID 40429966, 2025). "Similarly, UBC9ΔDC mice in the cecal ligation and puncture (CLP) sepsis model exhibit higher mortality rates than WT mice in the CLP sepsis model, with significantly elevated levels of IL-18 and IL-1β in plasma." (PMID 39234245, 2024). "Using cytokine injections and perturbations in vivo, we discovered a hierarchical cytokine module composed of TNF, IL-18, IFN-γ and IL-1β that sufficed to explain most of the organism-wide response to sepsis, ranging from genes to cells to tissue physiology and host fitness." (PMID 38191855, 2024). "Once formed, the NLRP3 inflammasome activates caspase-1, which subsequently mediates the cleavage of pro-IL-1β and pro-IL-18 and the secretion of their bioactive forms, important players in the systemic inflammation and cardiac dysfunction (and MOF) during sepsis." (PMID 39559354, 2024).
Sepsis (continued). "In our in vivo model of polymicrobial sepsis, the absence of PLXNC1 resulted in a more severe inflammatory immune response, markedly with higher levels of IL-1β and IL-18, the hallmark cytokines of inflammasome activity." (PMID 39169397, 2024). "We found that NLRP6-driven IL-18 but not IL-1β contributes to sepsis-induced lymphocyte death, which were found to be crucial for host defense." (PMID 38720893, 2024). "The results showed that the mRNA levels of IL-18, IL-1β, and procaspase-1 decreased after knockdown of USP5 in LPS-induced sepsis cell model, and overexpressed TXNIP in USP5 knockdown cells could upregulate the inflammatory factors." (PMID 37534934, 2023). "The present study showed that TXNIP knockdown significantly inhibited hippocampal microglia activation in the sepsis mice, while the NLRP3 and cleaved caspase-1 protein expression levels and the inflammatory factors, IL-1β and IL-18, were significantly reduced in the hippocampus." (PMID 35571246, 2022). "Previous studies have reported that NGAL, IL-18, and KIM-1 may be elevated in the setting of sepsis and CKD." (PMID 36371256, 2022). "Furthermore, Ac-YVAD-cmk reduced the forced expression of IL-18 in whole blood cells, in THP-1 cells, and also in sepsis-induced acute kidney injury." (PMID 35563469, 2022). "In addition, serum cytokine levels of IL-1β, IL-6, IL-8, IL-10, IL-12, IL-17A, IL-18, IFN-γ, TNF-α, and calprotectin were found to be elevated in sepsis." (PMID 34654467, 2021). "When analyzing patients on IMV, the best predictive model for extrapulmonary sepsis included APACHE II score, IL-18, Ang-2 and IL-1RA (AUC: 0.835, 95%CI: 0.716–0.954), and for pulmonary sepsis included APACHE II score, Ang-2 and ICAM-1 (AUC: 0.784, 95%CI: 0.666–0.902)." (PMID 34811434, 2021). "IL-18 may therefore be a useful therapeutic target for AOSD as well as a biomarker for differential diagnosis between AOSD and sepsis." (PMID 33868298, 2021). "IL-18, a cytokine upstream of the inflammatory cascade reaction, induces the massive synthesis of inflammatory cytokines (TNF, IL-1β), which are the key mediators of sepsis-induced organ injury." (PMID 35054259, 2021). "Otherwise, there was no prognostic impact about IL‐18 in adult patients with sepsis, and IL‐18 was a biomarker better differentiating sepsis and septic shock status than PCT, CRP, and WBC." (PMID 33378581, 2021). "Moreover, serum ACLY levels were correlated to platelet count, IL‐18 levels, and monocyte counts in pediatric patients with sepsis, implying the potential roles of ACLY in immunometabolic regulation in sepsis." (PMID 33378581, 2021). "Previous studies indicate that levels of C-reactive protein, procalcitonin, lactate, some cytokines such as interleukin 18 (IL-18) and white blood cells could help to distinguish between AOSD and sepsis." (PMID 33868298, 2021). "To explore whether AC-YVAD-CMK could affect the NLRP1 inflammasome signaling pathway to improve sepsis-induced acute kidney injury, we measured the expression levels of Caspas-1, NLRP-1, IL-1β, and IL-18 by Western blotting." (PMID 34222479, 2021). "Literature studies have investigated the role, both diagnostic and prognostic, of some biomarkers such as PCT, IL-6, IL-18, presepsin, etc., in patients with sepsis and septic shock without finding conclusive results." (PMID 34577843, 2021). "The results of the present study were consistent with previous reports, in that IL-6, IL-8, MCP-1, G-CSF, IFN-γ, and TNF-α were higher than in healthy subjects, but IL-18 and IL-17A were not significantly different between healthy subjects and sepsis patients." (PMID 34654467, 2021). "The results showed that AC-YVAD-CMK treatment significantly reduced the expression levels of Caspas-1, NLRP-1, IL-1β, and IL-18 compared with those of the CLP group, confirming that AC-YVAD-CMK could reduce pyroptosis and sepsis-induced acute kidney injury." (PMID 34222479, 2021).